H19 (H19 imprinted maternally expressed transcript)
Diseases named in the same sentence as H19 in open-access papers (continued):
Sharing a sentence is not in itself a finding about the gene and the disease.
cervical carcinoma (28 papers, 2005 to 2025). A carcinoma arising from either the exocervical squamous epithelium or the endocervical glandular epithelium. "Overall, these findings deepen our understanding of the molecular changes linked to high‐risk HPV infections and identify PI3K, MALAT1 and H19 as promising biomarkers and therapeutic targets for cervical cancer." (PMID 41261348, 2025). "H19 gene polymorphisms were found to have predictive value for clinicopathological features in cervical cancer patients." (PMID 38166752, 2024). "Conversely, the downregulation of H19 has been linked to increased proliferation of cervical cancer cells." (PMID 38166752, 2024). "Aberrant expression of H19 in cervical cancer tissues has also been associated with cancer progression, providing another example of the oncogenic potential of this molecule." (PMID 38166752, 2024). "In the reproductive tract, circulating H19 is higher in women with polycystic ovary syndrome (PCOS) compared to controls, and H19 has been identified as a potential diagnostic and prognostic marker for epithelial ovarian and cervical cancer." (PMID 32404103, 2020). "Then, we inferred that H19 SNPs was associated with the development and progression of cervical cancer." (PMID 31772651, 2019). "In cervical cancer, a sole study has found a high frequency of both loss of heterozygosity and loss of imprinting for H19 and IGF2 genes, suggesting that they participate in the molecular pathogenesis of cervical cancer." (PMID 16248899, 2005). "Our findings confirm the observations that rs217727 in H19 gene is associated with cervical cancer." (PMID 27765929, 2016). "In cervical cancer, H19 contributes to increased cell proliferation, migration and resistance to chemotherapy." (PMID 41261348, 2025). "Another study has reported that silencing of H19 results in decreased cell proliferation, induction of apoptosis, and cell cycle arrest in the cervical cancer cell lines OV90 and SKOV3." (PMID 38166752, 2024). "Serum H19 exhibited a specificity of nearly 95% in diagnosing cervical cancer, although its sensitivity was relatively low at 30.8%." (PMID 38166752, 2024). "In cervical cancer, H19 acts as a miR-138-5p sponge, reducing SIRT1 expression as a miR-138-5p target gene." (PMID 38166752, 2024). "H19 has the ability to enhance both independent growth and anchorage-specific growth of cervical cancer cell lines." (PMID 38166752, 2024). "A previous study on cervical carcinoma found similar uncoupling of H19 and IGF2 expression along with biallelic hypomethylation of H19." (PMID 37371750, 2023). "H19 was reported to enhance cell proliferation and anchorage-independent growth of cervical cancer lines." (PMID 32326624, 2020). "Kaplan-Meier curves were used to plot the influence of H19 SNPs and clinicopathological variables on 5 year survival rate in cervical cancer patients." (PMID 31772651, 2019). "More recently the elevated expression level of H19 was observed in cervical cancer cells, and was secreted into cultured supernatant via EVs." (PMID 29657282, 2017). "Both of these two studies focused on exploring a single lncRNA (H19 or HOTAIR) in relation to cervical cancer." (PMID 28977961, 2017). "Our findings provide novel insights into prognostic indicators for corpus uteri and cervical cancer, and promote the clinical utility of H19 for individualized cancer treatments." (PMID 27926484, 2017). "Kaplan-Meier analysis revealed that patients with uterine corpus cancer and higher H19 expression had a shorter OS (HR=2.710, p<0.05), while females with cervical cancer and increased H19 expression had a shorter RFS (HR=2.261, p<0.05)." (PMID 27926484, 2017). "H19 lncRNA was shown to promote cell proliferation, multicellular tumor spheroid formation and anchorage-independent growth of cervical cancer cells in vitro." (PMID 29657282, 2017).
cervical carcinoma (continued). "In sum, these results indicated that H19 serves as a prognostic indicator of RFS in cervical cancer patients." (PMID 27926484, 2017). "The level of H19 transcripts in 3 different cervical cancer cell lines and in 2 samples of cervical cancer from a woman diagnosed with cervical cancer was determined by PCR." (PMID 23984081, 2013). "Two recent papers have also reported abnormal expression of the H19 oncofetal gene due to deletions and/or abnormal imprinting in cervical cancer specimens." (PMID 23984081, 2013). "PCR was used to examine H19 expression in cervical cancer cell lines and in two samples from a patient with cervical carcinoma." (PMID 23984081, 2013). "Since it was not possible to test the impact of H19-DTA on CIN3 cells, the in vitro growth suppressive effects of the H19-DTA plasmid on 3 human derived cervical cancer cell lines: HeLa, CaSky and SW756, were examined." (PMID 23984081, 2013). "RT-PCR indicated expression of H19 in cervical cancer samples and in one of the three cell lines examined." (PMID 23984081, 2013). "Additionally, serum H19 has emerged as a potential biomarker for the diagnosis and monitoring of cervical cancer." (PMID 38166752, 2024). "Several lncRNAs, including HOTAIR, H19, mucosa-associated lymphoid tissue 1 (i.e., MALT1), growth arrest-specific 5 (i.e., GAS5), cervical carcinoma high expressed 1 (i.e., CCHE1), and Pvt1 oncogene (i.e., PVT1), are crucial in tumorigenesis, invasion, metastasis, and radio-resistance." (PMID 37081411, 2023). "However, genotypes TT in LncRNA H19 rs2839698 and GG in rs3741219 are related to some poor clinicopathological parameters of cervical cancer." (PMID 31772651, 2019). "Until now, no study presents a significant association of H19 SNPs with survival of cervical cancer patients." (PMID 31772651, 2019). "Although genotypes TT in LncRNA H19 rs2839698 and GG in rs3741219 are related to some poor clinicopathological parameters of cervical cancer, only pelvic lymph node status could predict 5 year patient survival significantly." (PMID 31772651, 2019). "Multivariate Cox regression analysis showed that high H19 expression could independently predict a poorer prognosis in cervical cancer patients (HR=4.099, p<0.05)." (PMID 27926484, 2017). "However, high H19 expression was associated with a shorter relapse-free survival (RFS; HR = 2.261, 95% CI = 1.077 - 4.747, p = 0.0310) in cervical cancer patients when compared with patients with low H19 expression." (PMID 27926484, 2017). "However, of the three human cervical cancer cell lines examined, only HeLa cells expressed H19 transcripts detectable by PCR." (PMID 23984081, 2013). "Also, the biological functions and molecular mechanisms of lncRNA H19 in cervical cancer and uterine corpus endometrioid cancer are worthy of further research to furnish experimental evidence for its utility as a potential biomarker of disease prognosis and precision treatment." (PMID 27926484, 2017). "(2021), who reported alterations in several lncRNAs, including H19, in HPV‐positive cervical cancer cells." (PMID 41261348, 2025). "lncRNA H19 sponges 4miR-138-5p, increasing SIRT1 leading to inhibition of apoptosis and proliferation in cervical cancer." (PMID 39912983, 2025). "LncRNA H19 sponges miR-138-5p, which directly targets SIRT1, and then affects progression of cervical cancer cells." (PMID 33390953, 2020). "It is possible that aberrant methylation in some CpGs in the IGF2/H19 imprinted domain such as the intron 3 CTCF site may be influencing loss of imprinting and the exclusive usage of IGF2 promoter 1, inducing IGF2 overexpression, as has been previously shown in cervical carcinomas." (PMID 23775149, 2014). "Two previous studies examined the expression of H19 and IGF2 genes in samples from cervical cancer patients." (PMID 23984081, 2013). "However, in contrast, H19 has been shown to upregulate SIRT1 and promote cervical cancer progression via sponging of miR-138-5p." (PMID 38166752, 2024).
cervical carcinoma (continued). "In addition, MALAT1, PVT1, H19, and XIST can promote cancer cell proliferation, invasion, and migration and play a role in the progression of cervical cancer." (PMID 35262965, 2022). "In cervical & endocervical cancer patients from the TCGA Cervical Cancer cohort (gene expression by RNAseq -- IlluminaHiSeq, pancan normalized, n=308), high H19 expression did not predict OS (p > 0.05)." (PMID 27926484, 2017). "In conclusion, we found that high lncRNA H19 expression predicted an inferior prognosis in two female cancers (uterine corpus endometrioid cancer and cervical cancer), as well as in non-female cancer patients." (PMID 27926484, 2017). "This study found that lncRNA H19 expression acts as a novel prognostic factor for uterine corpus endometrioid cancer and cervical cancer, as well as a prognostic indicator of non-female cancers." (PMID 27926484, 2017). "Thus, to provide a further initial indication of the ability of H19 to direct DTA expression in pre- and malignant cervical cancer cells, we used established cervical cancer cell models." (PMID 23984081, 2013).
coronary artery disease (27 papers, 2016 to 2024). "GWAS revealed that H19 rs217727, located at 11p15.5, was associated with altered susceptibility to systolic blood pressure and coronary artery disease." (PMID 38255915, 2024). "H19 polymorphism has been shown to be significantly associated with the risk of coronary artery disease, suggesting that H19 plays an important role in cardiac pathogenesis." (PMID 35637964, 2022). "One study reported that increased expression levels of lncRNA H19 in peripheral blood mononuclear cells were related with risk of coronary artery disease." (PMID 32907536, 2020). "Another study has illustrated an association between common H19 polymorphisms with the risk and severity of coronary artery disease in a Chinese population, and high expression of H19 was observed in the patients with AS." (PMID 31757932, 2019). "For example, SNP rs217727 in H19 is correlated with the risk of coronary artery disease in a Chinese population." (PMID 27626436, 2016). "The rs2067051 is located in the exon of H19 and is associated with a decreased risk of coronary artery disease in a Chinese population." (PMID 27626436, 2016). "lncRNA H19 (H19) elevation is related to the risk of coronary artery disease." (PMID 35345660, 2022). "Some studies reveal that increase of H19 is related to the risk of coronary artery disease." (PMID 35345660, 2022). "Moreover, an upregulated plasma level of H19 has already been flagged as a potential risk factor for coronary artery disease in a Chinese population." (PMID 31757932, 2019). "The increased risk of the rs217727 TT genotype in H19 was also observed in coronary artery disease." (PMID 31275455, 2019). "Furthermore, an H19 polymorphism was shown to possess a significant correlation with the risk of coronary artery diseases." (PMID 31588235, 2019). "Furthermore, individuals carrying the risk alleles of H19 display a higher risk of coronary artery disease." (PMID 31011482, 2019). "For example, upregulated lncRNA H19 has been documented in the blood of patients with coronary artery disease." (PMID 31757932, 2019). "The purpose of the present study was to investigate thecorrelation between the expression level of the H19 longnon-coding RNA and coronary artery disease." (PMID 30124004, 2019). "Recent studies reported that lncRNA H19 re-expresses in the artherosclerotic plaque and animal model of coronary artery disease." (PMID 28203482, 2017). "This may provide a potential upstream regulatory mechanism for H19 re-expression in ischemic heart diseases." (PMID 31588235, 2019). "Additionally, it has been noted that up-regulation of H19 in the whole blood of patients with coronary artery disease serves as a predictive marker for AS progression." (PMID 31757932, 2019). "Rs2067051 of H19 has been verified connected with birth weight and coronary artery disease." (PMID 30086750, 2018). "Univariate analysis revealed that admission NIHSS scores, age, EMT, coronary heart disease, atrial fibrillation, neutrophils counts, lymphocytes counts, NLR, and the expression level of H19 in lymphocytes were correlated with poor prognosis in AIS patients." (PMID 39204113, 2024). "Moreover, hyperhomocysteinemia, an independent risk factor for coronary artery diseases (CAD), increases the expression of H19 in aorta and vascular smooth muscle cells, indicating that upregulated H19 may participate in the progression of CAD, the most common cause of HF." (PMID 27317124, 2016). "A study has measured the circulating levels of H19 in the plasma samples from 300 patients with coronary artery disease (CAD) and 180 control subjects, which identified that plasma levels of H19 were increased in CAD patients with heart failure compared to those with normal cardiac function." (PMID 35139769, 2022).
lymph node metastasis (27 papers, 2009 to 2025). "CC/CT in LncRNA H19 rs2839698 exhibited less risk to have pelvic lymph node metastasis [Odds ratio (OR): 0.19, 95% Confidence interval (CI):0.04-0.82, p=0.028)], as compared with TT." (PMID 31772651, 2019). "A total of five studies reported the association between lncRNA H19 expression and lymph node metastasis." (PMID 27738631, 2016). "Sensitivity analysis was performed to assess the effect of individual study on the pooled ORs for the association between H19 expression and lymph node metastasis." (PMID 27738631, 2016). "It demonstrated that the group of high H19 expression had a higher risk of lymph node metastasis than those of low H19 expression." (PMID 27738631, 2016). "Furthermore, H19 is associated with key clinical factors such as tumor size, clinical stage, lymph node metastasis, distant metastasis, and overall survival (OS), with studies suggesting its potential as biomarker in the progression of tumors." (PMID 40004468, 2025). "The expression levels of H19 in cancer biopsy specimens and plasma increased dramatically, which was significantly associated with the expression of estrogen and progesterone receptors and lymph node metastasis." (PMID 33462225, 2021). "Moreover, exosomal H19 expression levels were associated with lymph node metastasis (p = 0.039), distant metastasis (p = 0.008), TNM stages (p = 0.022), ER (p = 0.009), PR (p = 0.018), and Her-2 (p = 0.021)." (PMID 34073560, 2021). "The multivariate analysis of this retrospective, non-randomised study including 89 patients with benign thyroid nodes and 410 patients with PTC confirmed that H19 could be an independent risk factor for the extrathyroidal extension and lymph node metastasis." (PMID 33158279, 2020). "High H19 expression was associated with more lymph node metastasis and distant metastasis." (PMID 32698890, 2020). "Finally, we analyzed the association between H19 and lymph node metastasis, and the result elaborated that lymph node metastasis occurred with the expression levels of H19 (OR = 2.04, 95% CI = 1.19–3.48, P = 0.009, random-effect)." (PMID 27672656, 2016). "From meta-analysis results, it found that the over-expressed H19 was associated with poor histological grade (OR=2.31, 95% CI: 1.12-4.75, p=0.02), positive lymph node metastasis (OR=2.29, 95% CI: 1.21-4.34, p=0.01), and advanced TNM stage (OR=4.83, 95% CI: 3.16-7.39, p<0.001)." (PMID 27825121, 2016). "Multivariate analysis showed that lymph node metastasis and low H19 expression were independent predictors of poor survival." (PMID 39659621, 2024). "Dugimont and Adriaenssens illustrated a correlation between H19 expression levels and pathological features such as lymph node metastasis, tumor grades, and the presence of estrogen and progesterone receptors that did not validate in the current research." (PMID 36274054, 2023). "Subsequently, multiple investigators have taken notice of the oncogenic role of H19; a study revealed that H19 expression was significantly correlated to ER, progesterone receptor, c-erbB-2, and lymph node metastasis in BC patients." (PMID 34421359, 2021). "We demonstrated overexpression of H19 in GC patients with aggressive disease and lymph node metastasis." (PMID 29088808, 2017). "In this meta-analysis, we found that high levels of H19 were more prone to lead to lymph node metastasis (OR = 2.04, 95% CI = 1.19–3.48, P = 0.009)." (PMID 27672656, 2016). "We firstly explored the correlation of H19 expression levels with lymph node metastasis and distant metastasis in cancers." (PMID 27672656, 2016). "As for clinicopathology, it showed that increased H19 was related to poor histological grades (OR=2.31, 95% CI: 1.12-4.75), positive lymph node metastasis (OR=2.29, 95 % CI: 1.21-4.34) and advanced clinical stage (OR=4.83, 95% CI: 3.16-7.39)." (PMID 27825121, 2016).
lymph node metastasis (continued). "Furthermore, H19 overexpression in melanoma patients was correlated with poor clinical prognosis, such as lymph node metastasis, distant metastasis, and shorter OS." (PMID 34421359, 2021). "Similarly, plasma H19 levels were significantly correlated with lymph node metastasis, and high plasma H19 levels were significantly reversed in postoperative samples." (PMID 31744046, 2019). "Increased H19 is significantly correlated to advanced TNM stage and lymph node metastasis, while leads to poorer overall survival in patients with STAD." (PMID 28484081, 2017). "Moreover, exosomal H19 expression levels were related to lymph node metastasis, distant metastasis, and TNM stages, all indicating the H19 potential as a non-invasive biomarker for BC diagnosis." (PMID 34707990, 2021). "No significant relation was found between gender, age, lymph node metastasis, administration of I131 and external beam irradiation and H19 expression." (PMID 31791180, 2019). "Our data showed that both H19 and miR-675 were expressed at higher levels in GC tissues than in noncancerous tissues, and H19 expression was positively correlated with lymph node metastasis and clinical stage." (PMID 24810858, 2014). "In addition, analysis in the preoperative and postoperative plasma samples showed the postoperative levels of circulating GAS5 and H19 significantly decreased, and circulating GAS5 levels in the patients with a positive lymph node metastasis state decreased after surgery." (PMID 31744046, 2019).